KRT8P32 (keratin 8 pseudogene 32)
Gene: Processed pseudogene on chromosome 5 (98,392,070 to 98,393,530, reverse strand). Ensembl gene ENSG00000250221.
Diseases named in the same sentence as KRT8P32 in open-access papers:
KRT8P32 is named in the same sentence as 1 disease in open-access papers, as found by Europe PMC text mining. Sharing a sentence is not in itself a finding about the gene and the disease. The quoted sentences say what the papers report.
breast carcinoma (1 paper, 2023). "For example, the pseudogene KRT8P32 has been identified in breast cancer and the pseudogene ACTBP11 was observed in GM12878 (B cells) cell lines according to Diana-LncBase V3." (PMID 37775701, 2023).